ID3 (inhibitor of DNA binding 3)
Diseases named in the same sentence as ID3 in open-access papers (continued):
Sharing a sentence is not in itself a finding about the gene and the disease.
prostate carcinoma (14 papers, 2006 to 2022). A carcinoma that arises from epithelial cells of the prostate gland. "In conclusion, our results clearly demonstrate that Id1 and Id3 expression is associated with prostate cancer progression." (PMID 23342268, 2012). "Of all the four Id proteins, the expression of Id1, Id2, and to a lesser extent, Id3 in prostate cancer and the underlying molecular mechanism is relatively well known." (PMID 23342267, 2012). "We propose that Id1 and Id3 together could have higher diagnostic and therapeutic value in prostate cancer." (PMID 23342268, 2012). "The results demonstrate that Id1 and Id3 expression is associated with prostate cancer." (PMID 23342268, 2012). "Interestingly a stronger statistical association was observed in case of Id3 with prostate cancer as compared with Id1: the difference between Id3 expression in normal versus grade II was more significant in post hoc Dunn's multiple comparison test (***P < 0.001) as compared with Id1 (*P < 0.05)." (PMID 23342268, 2012). "To recapitulate our findings in further cellular models, we depleted ID3 in human prostate cancer cells (Du145) and human osteosarcoma cells (U2OS) using a pool of four different specific siRNAs." (PMID 34718742, 2021). "It has been reported that GT3 treatment of prostate cancer LNCaP and PC3 cells causes upregulation of activated JNK and its target c-JUN via the downregulation of Id-3 and upregulation of MKK4." (PMID 32414345, 2020). "The expression of ID1, ID2, and at a lesser amount the ID3 genes were also investigated in several studies including prostate cancer researches and the relationship between their over-expression and cancer incidence was clearly perceived." (PMID 30876429, 2019). "This was also seen in prostate cancer, where Id1 and Id3 were induced by TGFβ to inhibit proliferation." (PMID 26865052, 2016). "Detailed cellular localization of Id1 and Id3 proteins in prostate cancer cell lines was investigated by immunocytochemistry (Id1 and Id3 expression shown in LNCaP and DU145 cells)." (PMID 23342268, 2012). "Our results show that targeting Id3 alone can reduce prostate cancer cell proliferation significantly more as compared with silencing Id1 alone." (PMID 23342268, 2012). "We also demonstrate that Id3 alone blocked proliferation of prostate cancer cells as compared with Id1." (PMID 23342268, 2012). "This study provides the first comprehensive analysis of Id1 and Id3 protein expression and localization in human prostate cancer." (PMID 23342268, 2012). "The purpose of this study was to investigate the expression and relevance of Id1 and Id3 proteins in prostate cancer." (PMID 23342268, 2012). "The localization of Id1 and Id3 is also consistent with their localization in prostate cancer tissue." (PMID 23342268, 2012). "We have previously reported that silencing either Id1 or Id3 in prostate cancer cell lines LNCaP and DU145 cells independently attenuated proliferation." (PMID 23342268, 2012). "In grade I and II prostate cancer specimens, Id3 expression was predominantly cytoplasmic to perinuclear, but in some cells intense nuclear Id3 expression was also observed." (PMID 23342268, 2012). "ID3 plays a role in TGFβ mediated cell migration in prostate cancer cells." (PMID 30301189, 2018). "We speculate that Id3 undergoes a distinct cytoplasmic-nuclear shuttling with increasing grades of prostate cancer, although the significance of this shuttling remains unclear." (PMID 23342268, 2012). "The increased expression of Id3 in prostate cancer is a novel observation." (PMID 23342268, 2012). "Our results suggest that increased Id1/Id3 could lead to downregulation of all three CDKNIs resulting in aggressive phenotype in prostate cancer." (PMID 23342268, 2012). "Aptamer or small molecule inhibitor that could target HLH domain of Id1 and Id3 could therefore be an ideal therapeutic approach in prostate cancer." (PMID 23342268, 2012).
prostate carcinoma (continued). "A very significant increase in Id3 expression was observed in prostate cancer (grade II)." (PMID 23342268, 2012). "Overall, a positive correlation between Id3 expression and prostate cancer grade was observed." (PMID 23342268, 2012). "Increased Id1 and Id3 expression could therefore significantly decrease the expression of CDKNIs as shown in this and other studies that could be a mechanism leading to aggressive phenotype in prostate cancer." (PMID 23342268, 2012). "The prostate cancer cell lines LNCaP and DU145 expressed Id1 and Id3 as determined by Western blot analysis (Id1 and Id3 in LNCaP and DU145)." (PMID 23342268, 2012). "Semiquantitative analysis of Id1 and Id3 expression in prostate cancer specimens using nonparametric Kruskal–Wallis analysis essentially validated our observations stated above: increased Id1 and Id3 expression was significantly associated with increasing grade of prostate cancer." (PMID 23342268, 2012). "BMP4 has also been shown to inhibit growth of the prostate cancer cell line LNCaP and induce the expression of ID1, ID2, and ID3 in cell lines." (PMID 16638148, 2006). "Also, TGF-β increased the expression of ID1 and ID3 in prostate cancer cell lines and so far, only lactoperoxidase was reported to decrease ID1 and ID3 expression on oral squamous oral epithelial cell line." (PMID 33477984, 2021). "A targeted network analysis of gene expression profiles in colorectal cancer cells revealed that ONC201 downregulates stem cell pathways such as Wnt signaling and modulates genes (ID1, ID2, ID3 and ALDH7A1) known to regulate self-renewal in colorectal, prostate cancer and glioblastoma." (PMID 28767654, 2017). "The intensity of Id3 staining in the nucleus increased dramatically in grade III cancers, although a weak cytoplasmic staining still persisted, a pattern which is similar to that observed in prostate cancer cell lines." (PMID 23342268, 2012). "The decrease in proliferation in cells lacking both Id1 and Id3 is also not significantly different from cells lacking Id3 alone, further suggesting a dominant role of Id3 in prostate cancer cell proliferation." (PMID 23342268, 2012). "Although we demonstrated that Id3 is expressed in prostate cancer cell lines, its expression in prostate tissue was not investigated." (PMID 23342268, 2012).
melanoma (13 papers, 2011 to 2025). A malignant, usually aggressive tumor composed of atypical, neoplastic melanocytes. "ID3 is also associated with chemoresistance, and depletion of ID3 increases the sensitivity of melanoma to short-term treatment with the BRAF inhibitor vemurafenib." (PMID 37170184, 2023). "Our study identified the gene encoding the transcriptional regulator ID3 as one that is upregulated by MEKi in multiple melanoma cell lines." (PMID 35187538, 2021). "Coordinate expression of Id1 or Id3 or CD44 with HAS2 or HAS3 or CD44 was found to be associated with reduced survival of human melanoma patients." (PMID 30297743, 2018). "Given that treatment with PD901 causes increased ID3 expression in each of our melanoma cell lines tested, we next sought to determine whether HSP70 inhibition could block this." (PMID 35187538, 2021). "ID3 is a transcriptional regulator implicated in the resistance of melanoma to BRAFi." (PMID 35187538, 2021). "We next sought to determine the impact of ID3 silencing and overexpression on the sensitivity of melanoma to MEK inhibition." (PMID 35187538, 2021). "We show that silencing ID3 enhances the sensitivity of melanoma to MEKi, thus mimicking the effect of the brain microenvironment." (PMID 35187538, 2021). "Repression of SOX10 expression was also suggested in melanoma cells which were upregulating ID3 after vemurafenib short-term stimulation." (PMID 31118886, 2019). "Our study reports a novel functional link between HA-CD44 interaction and BMP-induced Id1 and Id3 protein in melanoma." (PMID 30297743, 2018). "We therefore conclude that the CD44/HA axis can potentiate the ability of BMP4/7 to activate Id1 and Id3 expression in melanoma cells, thereby contributing to poor prognosis." (PMID 30297743, 2018). "ID3 expression is also higher in a model of doxorubicin-resistant melanoma cell line compared to its control cell line." (PMID 29299138, 2017). "To confirm the potential role of ID3 in the response of melanoma cells to drug treatment, we treated several melanoma cell lines with vemurafenib or in combination with trametinib." (PMID 29299138, 2017). "The regulation of TH9 cell differentiation by the transcription factor Id3 influences anti-melanoma immunity in an IL-9-dependent fashion." (PMID 27832300, 2017). "To acquire more insight into the mechanism of ID3 function in melanoma progression, we further characterized ID3 knockdown and ID3 overexpressing cell lines with respect to cell proliferation, cell migration and cell cycle states." (PMID 29299138, 2017). "On the same note, we observed in our laboratory, a 2-fold upregulation of ID3 expression in vemurafenib-treated melanoma cell lines compared to DMSO treatment." (PMID 29299138, 2017). "In this report, we identify ID3 as a new molecule involved in melanoma adaptive resistance to vemurafenib and in the regulation of melanoma migration." (PMID 29299138, 2017). "In this report, we show that melanoma cells upregulate ID3 expression (and also ID1 and ID2) in response to vemurafenib (or to the combination vemurafenib + trametinib) in vitro and in patients’ tumors." (PMID 29299138, 2017). "BMDC expression of transmembrane receptor VLA-4 (also known as integrin α4β1) and inhibitor of differentiation 3 (Id3, a protein involved in regulation of the immune response in melanomas) enhanced pre-metastatic cluster formation by augmenting adhesion among HPCs and migration of HPCs." (PMID 35740692, 2022). "Treg signature genes CXCR5, TNFRSF9, CCR7, STAT1, GBP4, and EOMES were significantly upregulated in the young cohort and were correlated with higher survival in melanoma, while ID3, IL-17A, IL-17F, RDH10 and IL-11 were significantly upregulated in the old cohort." (PMID 36135194, 2022).
melanoma (continued). "Inhibitor of differentiation protein 3 (ID3) is another player highly involved in phenotype switching; the transcription profiling of 21 BRAF-mutated melanomas revealed an upregulation of ID3 in BRAF inhibitor (BRAFi)-resistant tumors compared to treatment-naïves." (PMID 36551603, 2022). "We show that silencing ID3 increases melanoma sensitivity to MEK inhibitors." (PMID 35187538, 2021). "Moreover ID3 silencing leads to an increased melanoma sensitivity to vemurafenib short-term treatment." (PMID 31118886, 2019). "The tumor-promoting properties of these transcriptional regulators, and the ability of the HA/CD44 axis to promote their expression in response to BMP stimulation, likely underlies the association between coordinate expression of Id1/Id3 and HAS2/HAS3/CD44, and reduced survival of melanoma patients." (PMID 30297743, 2018). "Next we determined whether CD44, the principal cell surface receptor for HA, plays a role in the ability of HA to stimulate BMP-induced Id1 and Id3 expression in B16-F10 and Ret melanoma cells." (PMID 30297743, 2018). "To further substantiate the notion that HA promotes BMP4/7-induced Id1/Id3 expression in melanoma cells, we treated the cells with 4-MU, a 7-hydroxy-4-methylcoumarin that inhibits HA synthesis by depleting cellular UDP-glucuronic acid and downregulating HA synthase expression." (PMID 30297743, 2018). "We therefore investigated whether HA in the pericellular matrix might play a similar role in regulating BMP-induced Id1/Id3 expression in B16-F10 and Ret melanoma cells." (PMID 30297743, 2018). "Increased BMP-induced Id1/Id3 expression in response to HA could act at a number of levels to promote melanoma formation and progression." (PMID 30297743, 2018). "Together, these data show that vemurafenib treatment or combination treatment with trametinib upregulate ID3 expression and that, changes in ID3 expression level can regulate early resistance of melanoma cells, suggesting a role for ID3 in adaptive resistance to these drugs." (PMID 29299138, 2017). "Ultimately, we found that the absence of ID3 sensitizes melanoma cells to vemurafenib treatment, suggesting that ID3 or ID3 downstream targets’ pharmacological inhibition may help improving current treatment targeting resistant melanoma." (PMID 29299138, 2017). "Thus, these preliminary data suggested that vemurafenib treatment leads to dedifferentiation of melanoma cells and to an upregulation of ID3 expression." (PMID 29299138, 2017). "The upregulation of ID3 following PD901 treatment, and inhibition of this by ACM, was confirmed in several melanoma lines (WM4265.2, WM983B, and 1205Lu) at the RNA (qRT-qPCR) and protein levels." (PMID 35187538, 2021). "We identify ID3 as a novel client protein of HSP70, and show that the HSP70 inhibitor AP-4–139B synergizes with MEK inhibitors against NRAS-mutant melanoma in vivo." (PMID 35187538, 2021). "Further inspection of the RNA-seq data revealed that the expression of ID3 was upregulated by PD901, but this was abrogated when melanomas were cultured in ACM (arrow)." (PMID 35187538, 2021). "We also observed that inhibitor of differentiation 3 (ID3), which belongs to the helix-loop-helix (HLH) TF superfamily, is upregulated in the tumors of melanoma patients after their treatment with a BRAF inhibitor, when compared to before the treatment." (PMID 31118886, 2019). "Our data also suggest a repression of SOX10 by ID3 and a role of the ID3-SOX10 axis in melanoma drug resistance." (PMID 29299138, 2017). "Melanoma cells were surface stained for TSPAN8, RELN and FXYD5 or intracellularly stained for renalase, CAPG, BCL11A and ID3." (PMID 21081927, 2011). "Studies have reported upregulation of ID3 (inhibitor of differentiation 3, a helix-loop-helix TF superfamily member) in melanomas of patients treated with a BRAF inhibitor, and silencing ID3 resulted in enhanced sensitization of melanoma to vemurafenib." (PMID 40558548, 2025).
melanoma (continued). "ID3 (inhibitor of differentiation) and ABCB5 (subfamily B, member 5) transporter (a member of the ATP-binding cassette (ABC) superfamily) overexpression is reported in VemR melanomas." (PMID 40558548, 2025). "We show that MEK inhibitors cause upregulation of inhibitor of differentiation protein 3 (ID3), but not when melanomas are cultured in ACM." (PMID 35187538, 2021). "Targeting Id1 and Id3 protein expression by perturbation of the HA-CD44 interaction might be a promising and effective approach for melanoma therapy." (PMID 30297743, 2018). "It is noteworthy that these results are supported by another study showing that the regulation of TH9 cell differentiation by the transcription factor Id3 regulated anti-melanoma immunity in an IL-9-dependent manner but without affecting TH1 cell responses." (PMID 27832300, 2017). "In sum, these results show that ID3 controls melanoma cell migration and regulates mesenchymal markers, without affecting cell proliferation or cell cycle states." (PMID 29299138, 2017). "The ability of ID3 to contribute to the resistance to MEKi in both NRAS-mutant (WM4265.2, M93–047) and BRAF-mutant (1205Lu, WM983B) melanomas suggested that it might be a good therapeutic target for melanoma." (PMID 35187538, 2021). "In addition, our findings present a regulation of melanoma cell migration by ID3 without influencing their proliferation or their cell cycle states." (PMID 29299138, 2017). "Interestingly, neither ID3 knockdown nor ID3 overexpression had a significant impact on melanoma cell lines’ proliferation rate as quantified by alamar blue staining over a period of 5 days." (PMID 29299138, 2017). "In addition, if disseminating melanoma cells settle in an HA-rich microenvironment with only low concentrations of BMPs, then melanoma metastasis formation may be fostered by HA-stimulated BMP-induced Id1/Id3 expression due to the tumor-initiating properties endowed on cancer cells by Id1 and Id3." (PMID 30297743, 2018).
ovarian carcinoma (9 papers, 2001 to 2023). A malignant neoplasm originating from the surface ovarian epithelium. "A search was conducted for mutations of Id3 in primary ovarian cancers using single stranded conformation polymorphism (SSCP) analysis." (PMID 11161400, 2001). "In addition, BMP4 signaling causes direct overexpression of ID3, a proto-oncogene that contributes to the pathogenesis of human ovarian cancer." (PMID 28947976, 2017). "Aside from these findings, loss of ID3 expression was demonstrated in ovarian cancer." (PMID 18513385, 2008). "In support of this, targeting the ID1/ID3 interaction with the E47 bHLH transcription factor is effective against breast and ovarian cancers." (PMID 35187538, 2021). "BMP4 promotes migration and metastasis in ovarian cancer and BMP4 stimulation of ovarian cancer cells can activate ID3 proto-oncogene expression." (PMID 26755648, 2016). "In this study, we investigated the role of the peptide aptamer Id1/3-PA7 on the progression of cell cycle and apoptosis in Id1- and Id3-overexpressing ovarian cancer cells ES-2 and PA-1." (PMID 20842131, 2010). "Here, we used Id1/3-PA7 to analyse its functional interference in Id1- and Id3-overexpressing ovarian cancer cells ES-2 and PA-1." (PMID 20842131, 2010). "In various forms of tumours, including ovarian cancer, Id1 and Id3 are overexpressed extensively and in an overlapping pattern." (PMID 20842131, 2010). "Peptide aptamer Id1/3-PA7 significantly inhibited proliferation and induced apoptosis in ovarian cancer cells, with deregulated expression of Id1 and Id3." (PMID 20842131, 2010). "One of the genes under-expressed in the ovarian cancer cell lines, Id3, a transcriptional inactivator, was selected for further investigation." (PMID 11161400, 2001). "Furthermore, we have shown that the biological effects of Id1/3-PA7, in analysed breast and ovarian cancer cells, were counteracted by forced expression of Id1 and Id3." (PMID 20842131, 2010). "Moreover, since higher ID3 mRNA levels were associated with poor survival, further functional studies are needed to validate whether ID3 might in addition act as a “driver” of pathogenesis of ovarian cancer." (PMID 27527602, 2016). "The resulting two main clusters for ovarian cancer cell lines accentuate the expression differences for APOBEC3B, APOBEC3C, and APOBEC3G as well as of ID2 and ID3." (PMID 27527602, 2016). "Id3 mRNA was expressed at reduced levels in 6 out of 9 ovarian cancer cell lines compared to the HOSE cells while at the protein level, all 7 ovarian cancer cell lines examined expressed the Id3 protein at greatly reduced levels." (PMID 11161400, 2001). "This could indicate that in PA-1 and ES-2 ovarian cancer cells, Id1/3-PA7 might preferentially inhibit the heterodimerisation of Id1 and Id3 with ETS proteins, which are the positive regulators of CDKN2A." (PMID 20842131, 2010). "Therefore, we investigated the biological effect of the peptide aptamer Id1/3-PA7 in Id1/Id3-overexpressing and CDKN2A-positive ovarian cancer cells, ES-2 and PA-1." (PMID 20842131, 2010). "In ovarian cancer, we have shown that STIP1 binds to a bone morphogenetic protein (BMP) receptor – termed activin A receptor, type II-like kinase 2 (ALK2) – to activate the SMAD signaling pathway and the transcriptional activation of ID3 (inhibitor of DNA binding 3)." (PMID 23468915, 2013).